ZMAT2 (zinc finger matrin-type 2)
Description:
Involved in pre-mRNA splicing as a component of the spliceosome.
Synonyms: FLJ31121; hSNU23; Snu23; Ptg-12
Tractability: Small molecule: a structure with a bound ligand is known. PROTAC: UniProt records ubiquitination sites on it; ubiquitination databases record sites on it; its protein half-life has been measured.
Gene: Protein-coding gene on chromosome 5 (140,698,680 to 140,706,686, forward strand). Ensembl gene ENSG00000146007.
Subcellular location: Nucleus
Subcellular location (Human Protein Atlas): Mitochondria; Nucleoplasm
Pathways (Reactome):
Metabolism of RNA: mRNA Splicing - Major Pathway
Gene Ontology:
Molecular function: protein binding; nucleic acid binding; zinc ion binding
Biological process: mRNA splicing, via spliceosome
Cellular component: nucleus; U2-type precatalytic spliceosome; nucleoplasm; U4/U6 x U5 tri-snRNP complex; spliceosomal complex
Genetic constraint (gnomAD): Loss-of-function variants: 5 observed, 28.23 expected, observed/expected ratio (o/e) 0.18, 90% interval 0.092 to 0.37. The upper end of that interval is the gene's LOEUF score, 0.37, which puts it in group 1 of 6, group 1 being the genes least tolerant of losing a copy. Missense variants: 124 observed, 257.09 expected, observed/expected ratio (o/e) 0.48, 90% interval 0.42 to 0.56. Synonymous variants: 76 observed, 83.42 expected, observed/expected ratio (o/e) 0.91, 90% interval 0.76 to 1.1.
Homologues: Orthologues: chimpanzee ZMAT2 (100% identical), dog ZMAT2 (100% identical), mouse Zmat2 (100% identical), rabbit ZMAT2 (100% identical), guinea pig ZMAT2 (99% identical), pig ZMAT2 (99% identical), rat Zmat2 (99% identical), macaque ZMAT2 (97% identical), tropical clawed frog zmat2 (90% identical), zebrafish zmat2 (89% identical), Drosophila melanogaster CG11586 (57% identical). Paralogues in human: ZNF385B (22% identical), ZNF385D (21% identical), ZNF385C (20% identical), ZNF385A (16% identical), ZMAT1 (14% identical), ZNF346 (14% identical), ZMAT4 (13% identical), ZMAT3 (12% identical), KRCC1 (5% identical).
Diseases named in the same sentence as ZMAT2 in open-access papers:
ZMAT2 is named in the same sentence as 11 diseases in open-access papers, as found by Europe PMC text mining. Sharing a sentence is not in itself a finding about the gene and the disease. The quoted sentences say what the papers report.
depression (3 papers, 2021 to 2024). "The results of a recent study indicate that ZMAT2, a gene from the same family as ZMAT3, is a significant transcriptome-wide risk gene for depression and shows a strong association with depression in the brain expression quantitative loci data set." (PMID 37547246, 2023). "Many of these genes have been previously linked to brain-related disorders, including Alzheimer’s disease (WDR12, AGFG2, and CDK5RAP3), schizophrenia (SRA1, WDR55, CORO7, DDAH2, PCDHA8), autism spectrum disorder (MAPK3, PCDHA13), and major depressive disorder (ZMAT2 and ITIH4)." (PMID 39269986, 2024). "Seven out of 53 risk genes (B3GALTL, FADS1, TCTEX1D1, XPNPEP3, ZMAT2, ZNF501 and ZNF502) showed TWS associations with depression in two independent brain expression quantitative loci (eQTL) datasets, suggesting that these genes may represent promising candidates." (PMID 34021117, 2021).
schizophrenia (3 papers, 2021 to 2025). A major psychotic disorder characterized by abnormalities in the perception or expression of reality. "Regarding intelligence and schizophrenia, MAAT identified 21 genes with high association levels in these two traits, where the significant function of ACTR1A, C22orf46, CKB, CYP2D6, LRRC37A, NCK1, and ZMAT2 have been well validated in large-scale GWAS studies." (PMID 39905509, 2025).
ZMAT2 also shares sentences with these, for which no sentence is quoted: Alzheimer disease (1 paper); autism spectrum disorder (1); breast carcinoma (1); colorectal cancer (1); lung carcinoma (1); neurological diseases (1); ovarian carcinoma (1); prostate carcinoma (1); type 1 diabetes mellitus (1).